AKT1 (AKT serine/threonine kinase 1)
Diseases named in the same sentence as AKT1 in open-access papers (continued):
Sharing a sentence is not in itself a finding about the gene and the disease.
tumor (continued). "In that study, AKT-1 was shown to operate via the modulation of Bcl-2 and long-lived DC vaccines were potent enough to suppress tumor growth in the therapeutic setting and significantly increased mice survival." (PMID 23870437, 2013). "Tumor tissues were tested for HER2-status and mutations in the PTEN, PIK3CA, AKT1, CTNNB1, and E-cadherin type 1 genes." (PMID 23930209, 2013). "Akt1 overexpression reversed the osteosclerotic phenotype associated with DU145 cells to an osteolytic phenotype and enhanced intra-osseous tumor growth." (PMID 23902739, 2013). "As PIK3CA and AKT1 are oncogenes activated by mutations and as PIK3R1 and PTEN are tumor suppressors mainly inactivated by underexpression, respectively, all these alterations result in PI3K pathway activation." (PMID 24229379, 2013). "In an effort to determine the biological significance of Akt/CXCR4 axis in tumor growth, we subcutaneously implanted both low Akt1 (Neo) and high Akt1 (HA-Akt1) expressing cells in SCID mice." (PMID 23902739, 2013). "In our MTB-IGFIR transgenic mice, we found that Akt1 or Akt2 ablation significantly increased in tumor latency and decreased tumor growth rate." (PMID 23919516, 2013). "Seventy-four primary tumour samples were analyzed for Akt1, Akt2, pAkt Thr308 and pAkt Ser408 expression and scored." (PMID 22842582, 2012). "A previous cell line study of mouse embryonic fibroblasts and human colon, lung, cervix, skin and pancreas tumours showed that PINCH was radio-resistant by activating Akt1." (PMID 22325464, 2012). "PIK3CA, HRAS and AKT1 (all n = 1) mutations were detected in FFPE tumor specimens, while NRAS, PIK3CA and AKT1 (all n = 1) mutations were found in cpDNA samples." (PMID 23144797, 2012). "GUCY2C recently emerged as an intestinal tumor suppressor coordinating AKT1-dependent crypt-villus homeostasis." (PMID 22384056, 2012). "All results from individual PCR analyses agreed with array results with one exception; in tumor tissue with high compared to low COX-2 expression AKT1 expression was significantly higher in PCR analyses, with opposite direction in array analysis." (PMID 21668942, 2011). "They both were also positively associated with cytoplasmic Akt1 expression (p = 0.054 for HER3 and p = 0.0002 for HER4) and increased tumour grade." (PMID 21407808, 2011). "PTEN is a tumor suppressor gene and an antagonistic inhibitor of AKT1 (inactivation of PTEN leads to the activation of AKT1)." (PMID 21321378, 2010). "Mutational hotspots in AKT1 and in the regulatory and catalytic subunits of PI3K have been detected in multiple tumour types." (PMID 20407443, 2010). "Only a minor anti-tumor activity was noted, even though the compound inhibited the phosphorylation of Akt1/2 in the growing tumors." (PMID 21179398, 2010). "Tumours from bitransgenic mice overexpress the myr-Akt1 and ErbB2 transgenes, but there was dramatically less overexpression and phosphorylation of ErbB3, diminished phosphorylation of ErbB2, decreased level of EGFR protein and undetectable ErbB4 protein." (PMID 18700973, 2008). "The myr-Akt1 transgene in the bitransgenic tumours was phosphorylated at Ser473, indicating enzymatic activity, and can be distinguished from endogenous Akt because the myr-Akt1 transgene has a higher molecular weight." (PMID 18700973, 2008). "Expression of the HA-tagged myr-Akt1 transgene was only detected in tumour tissue from the bitransgenic animals." (PMID 18700973, 2008). "It was also shown that in different tumor cell backgrounds inhibition of mTOR was less effective in inducing caspase-3 activity than inhibition of Akt1 and Akt2." (PMID 19384426, 2007).
tumor (continued). "When Akt1 was constitutively expressed the mice developed tumours at a much faster rate than in those that only expressed HER-2." (PMID 16168126, 2005). "In the present study we analyzed the expression and activation of Akt-1 in relation to some factors involved in its pathway as well as other tumour characteristics." (PMID 11870534, 2002). "Overall positive percent agreement (PPA) for short variants across ctDNA tumor fraction (TF) subgroups in paired biopsy samples was: ctDNA TF ≥ 10%: PIK3CA, 93.9%; AKT1, 100%; PTEN, 100%; ctDNA TF 1%-10%: PIK3CA, 96.3%; AKT1, 100%; PTEN, 100%; ctDNA TF < 1%: PIK3CA, 34.7%; AKT1, 50.0%; PTEN, 37.5%." (PMID 40597213, 2025). "Although we did not examine concordance of results in the liquid versus the tissue biopsy cohort for alterations in genes other than PIK3CA, PTEN, AKT1, AKT2, and AKT3, our results support the value of blood-based NGS panel testing in providing a comprehensive tumor mutational landscape." (PMID 40597213, 2025). "CYPJ promotes TAMs repolarization towards the M1 phenotype by inhibiting the activity of AKT1 and enhancing the innate and adaptive immune responses, thereby facilitating the killing of tumor cells, which sheds light on the potential development of macrophage therapies for LIHC." (PMID 40520002, 2025). "Likewise, the combination therapy suppressed tumor progression by reducing AKT1 expression (p < 0.001) and increasing E‐cadherin expression (p < 0.01)." (PMID 40553053, 2025). "This case report describes a patient with metastatic PSP and AKT1 E17K mutation without PD-L1 expression in the tumor." (PMID 39758787, 2025). "Taken together, these results suggest that AKT1 E17K mutations may serve as a predictive biomarker across multiple tumor types, supporting the potential for AKT-targeted therapies in a pan-tumor approach." (PMID 40576713, 2025). "Furthermore, Maelstrom (MAEL) increases phosphorylated Akt1 expression in tumor cells, which phosphorylates the NF-κB subunit RelA, resulting in MDSC chemotaxis through the upregulation of CXCL8, thereby accelerating tumor progression within the TME." (PMID 40134607, 2025). "Additionally, IHC analysis revealed a significant reduction in the phosphorylation levels of Akt1 and Bad in the tumor lesions of the 4-NQO + Bru group compared to the 4-NQO group." (PMID 40563453, 2025). "CircNRIP1 acts as a tumor promotor in GC by absorbing miR-149-5p to influence AKT1 expression." (PMID 41299506, 2025). "Due to the significant role of Akt1 in tumor progression and drug resistance, coupled with the documented efficacy of flavonoids in targeting the PI3K/Akt/mTOR pathway, the present study aimed to evaluate the binding affinity of a set of 61 herbal flavonoids to the Akt1 ATP‐binding domain." (PMID 40798865, 2025). "However, PTEN is not expressed by LNCaP54 and cholesterol ester is down; therefore, rerouting to induce AKT1 activation to support tumour growth occurs by other means in LNCaP cells, namely via direct cholesterol use55." (PMID 39755726, 2025). "Amplification of AKT1 gene represents a frequent oncogenic alteration across multiple tumor types." (PMID 40746599, 2025). "The recognition of EZH2, EGF, and AKT1 as pivotal toxicological targets in PCBs-mediated breast carcinogenesis provides critical insights into the molecular pathways through which PCBs facilitate tumor progression." (PMID 40584614, 2025). "Our observations indicate that medicarpin may inhibit these processes by targeting both upstream and downstream components, including PIK3CA, AKT1, and mTOR, therefore resensitizing tumor cells to apoptotic signals." (PMID 41516052, 2025). "The aim of this study was to quantify the expression levels of the immune checkpoint molecules TIM-3 and Gal-9 in CRC tissues and adjacent non-tumor tissue, and to investigate their associations with key oncogenic mutations, including KRAS, NRAS, BRAF, PIK3CA, and AKT1, as well as MSI status." (PMID 40724985, 2025).
tumor (continued). "Furthermore, pharmacological inhibition or genetic knockdown of AKT1 upregulates ΔNp63α in vitro and suppresses tumor metastasis in vivo." (PMID 40223122, 2025). "We then investigated whether Akt1 or Akt2 signaling also enabled the tumor-specific CTLs to overcome TME in the oncogene-induced HCC mouse model." (PMID 40139836, 2025). "PDZK1 promotes tumor development by regulating the phosphorylation of AKT1." (PMID 38669103, 2024). "Thus, CHUK, IKBKB gene products, and co-chaperones FKBP5 (FKBP51), TSC1, and TSC2 interact with Hsp90 and behave like tumor suppressors, while AKT1 shows oncogenic behavior and is involved in the enhanced activity of many signaling pathways." (PMID 39337357, 2024). "Additionally, the AKT1 gene exhibited a considerable role in tumor pathways, cell proliferation and growth, and is involved in apoptosis." (PMID 39502516, 2024). "Thus, the formation of positive feedback loop between inactivated cGAS‐STING signaling and hyperactivated AKT1 is a crucial determinant of endocrine resistance by mediating immunosuppressive microenvironment and promoting tumor proliferation." (PMID 39023171, 2024). "Furthermore, while the mice with all other KO cell lines died eventually due to tumor progression, ~36% of the host mice implanted with Akt1/2/3KO cells experienced spontaneous tumor regression, leading to long-term tumor-free survival." (PMID 38920688, 2024). "Another study demonstrates the critical role of AKT1 in tumor angiogenesis." (PMID 39564104, 2024). "In animal models of CRPC, knockdown of AKT1/2 resulted in a significant reduction in tumor metastases, indicating that inhibition of AKT1 expression may improve survival prognosis for CRPC patients." (PMID 38326539, 2024). "We speculate that CSS may regulate the activity of immune‐related factors in the tumour microenvironment, reverse immune escape, enhance immune responses through AKT1, MAPK3, and CASP3, and synergistically alleviate HCC." (PMID 38613352, 2024). "Additionally, miR-185 has been shown to have a tumor-suppressive effect in HCC cells by inducing autophagy through regulation of the Akt1 pathway." (PMID 39273339, 2024). "In conclusion, CSS may regulate the activity of immune‐related factors in the tumour microenvironment, reverse immune escape, enhance immune responses through AKT1, MAPK3, and CASP3, and synergistically alleviate HCC." (PMID 38613352, 2024). "Notably, TRIB3 is key stress regulators in a variety of tumors because its C-terminal domain can interact with ubiquitin ligases and various other proteins to promote tumor progression, such as AKT1, β-catenin, SQSTM1, TRIM8, EGFR, and TCF4." (PMID 39881875, 2024). "Moreover, Zhang and his colleagues demonstrated that circNRIP1 sponges miR-149-5p to modify AKT1 expression levels and ultimately functions as a tumor promoter in GC." (PMID 38192436, 2024). "The presence of AKT1 polarized macrophages toward a pro-tumor phenotype." (PMID 38719996, 2024). "However, it is generally accepted that AKT1 plays an important role in the early stages of tumor development (tumor initiation and proliferation), while AKT2 primarily assists in tumor metastasis." (PMID 39057065, 2024). "We confirmed that Akt1/2/3KO cells were capable of anchorage-independent growth by a 3D culture; therefore, it was not the cause of slower tumor growth in vivo." (PMID 38920688, 2024). "The expression of AKT1 is also related to tumor invasion and migration." (PMID 38233930, 2024).
tumor (continued). "Next, immunostaining for AKT1 in paired tumor-free and tumor-containing lymph node specimens showed significantly higher co-localization of AKT1 with macrophages (marked by CD68) in the tumor-containing lymph node compared to the tumor-free lymph node from the same patient." (PMID 38719996, 2024). "HSP90α and AKT1 were the key targets that sciadopitysin plays anti-tumor effects." (PMID 38911393, 2024). "Interestingly, we found that while the AKT2 and AKT3 KO WM1799 cells developed tumors similarly to NT cells, only the AKT1 KO cells had significantly delayed tumor growth." (PMID 37894325, 2023). "Further, we observed no change in total AKT phosphorylation across those tumors in which AKT2 was depleted, suggesting AKT1 or AKT3 activity may compensate over time to promote tumor growth." (PMID 37894325, 2023). "In addition, NOP14 induced expression of transcription factor E2F4 independent of miR17-5p/P130 signaling, which simultaneously activated a set of targeted genes, such as CCNE1, PIM1, AKT1 etc., to promote tumor proliferation." (PMID 37506248, 2023). "We further tested whether AKT1 played a role in anchorage-independent growth, as the AKT1 KO WM1799 cells showed not only delayed tumor formation but also a reduction in tumor growth." (PMID 37894325, 2023). "While ectopic expression of AKT1-DD alone showed some activity, co-expression of MAPK4D254A further enhanced cell growth, and the activity of co-expressed MAPK4D254A and AKT1-DD largely recapitulated WT MAPK4 tumor-promoting activity in the proliferation assays." (PMID 37531320, 2023). "Moreover, AKT1/2 KO enhanced tumor killing of TIL against tumor cell lines HeLa or Hey‐T30 compared with the control group." (PMID 36028997, 2023). "Cluster 1 comprises genes important for skeletal muscle (ACTA1) and muscle function (ACTN1) and includes a crucial gene (AKT1) known to regulate insulin signaling, cell survival, and tumor progression, as well as two chaperones: HSPA1A and HSPB1 (heat shock proteins (HSPs))." (PMID 36767649, 2023). "We further tested whether AKT1/2 KO could promote anti‐tumor function of TIL in a manner similar to that seen in AKT inhibition." (PMID 36028997, 2023). "Moreover, these core genes (Pik3r1, Akt1, Myc, Egfr, Hif1a, Vegfr, Jun, and Stat3) are closely related to the tumor immune microenvironment, exclusively T cell immune function." (PMID 37799727, 2023). "AKT1 is responsible for repressing dexamethasone-induced tumor cell apoptosis." (PMID 37046703, 2023). "Truqap (capivasertib) is an oral selective adenosine triphosphate (ATP) competitive inhibitor of all three isoforms of the serine/threonine kinase AKT (AKT 1/2/3), which is designed to work by targeting mutations in the AKT1 gene, which is responsible for tumor growth and proliferation." (PMID 38069380, 2023). "Knockout Akt1 eliminated the function of 5-HT in promoting tumor cells." (PMID 35664068, 2022). "Similarly, the results also showed that Akt1 predominantly regulated retinal angiogenesis, tumor angiogenesis, EC proliferation, EC sprouting, Notch3 activation, and the inhibition of YAP." (PMID 35931736, 2022). "Importantly, Akt-mTOR activation was significantly inhibited in SKI-V-treated pCCa-1 tumor tissues, as the levels of phosphorylated Akt1 and S6K were dramatically decreased." (PMID 35541904, 2022). "During tumorigenesis, AKT1 may have opposite effects, may act as a pro-oncogenic factor suppressing apoptosis, or may restrict the tumor invasion." (PMID 36077529, 2022). "A variety of bioactive ingredients in the formula could play roles in regulating CASP3, AKT1, and other genes in immune, infection, apoptosis, and tumor-related signaling pathways." (PMID 36212968, 2022).
tumor (continued). "NI‐WB revealed that 31/32 (96.9%) of tumor has lower phospho‐Akt1/2/3 compared to matched mucosa." (PMID 34919787, 2022). "Moreover, OCs can be divided in type I (low-grade tumor with BRAF and KRAS mutations) or type II (high-grade tumor with a variety of mutations including HOX, PTEN, KRAS, AKT1, BRCA1/2 genes) and various dysregulated mechanisms underlying the pathology." (PMID 36191006, 2022). "The majority of samples for determination of PIK3CA/AKT1/PTEN status were from primary tumor tissue (143 [64%] primary, 66 [30%] metastatic, 10 [5%] unknown, three [1%] enrolled based on local testing with no central confirmation available)." (PMID 34860318, 2022). "The phospho‐Akt1/2/3 levels in tumor are significantly lower than matched mucosa." (PMID 34919787, 2022). "Indeed, poor prognosis and high hazard ratios were found associated with PTEN-low/miRNA-low high RhoA signalling in the BL-1 tumours, AKT1 copy gain/high mRNA expression in the BL-2, and high programmed cell death 1 (PD1) expression in IM." (PMID 36077812, 2022). "In this regard, targeting the Akt1/mTOR/DNA-PK signaling axis could be critical for limiting ERMS tumor regrowth and recurrence." (PMID 36139434, 2022). "We try to explain the result in this way: The proliferation and development of CAFs are regulated by PI3K/AKT/mTOR signaling pathway, and CAFs might promote tumor progress via IGF1R/AKT1/mTOR pathway in tumor microenvironment." (PMID 35768785, 2022). "Tumor phospho‐Akt1/2/3 is significantly higher in right‐sided compared to left‐sided tumor." (PMID 34919787, 2022). "After adjusting tumor purity, the expression of ALOX12B was negatively associated with IGFR1, AKT1, MTOR, and EIF4EBP1, and the same correlation could also be observed in SPRR1A." (PMID 35768785, 2022). "Finally, AKT1 was upregulated in CLs, while AKT3 was downregulated across all sample groups except for basal-like TN tumours, while AKT antagonising factors such as PTEN were only downregulated in CLs and normal-like TN tumours." (PMID 36220861, 2022). "Moreover, Akt1 overexpression reversed the osteosclerotic phenotype to an osteolytic phenotype and promoted intra-osseous tumor growth." (PMID 36059977, 2022). "AKT1 is related to tumor development and metastasis in HCC and is activated by the PI3K pathway." (PMID 36234758, 2022). "AKT1 is involved in regulating PI3K/AKT/mTOR, a tumor-generating pathway." (PMID 35603567, 2022). "AKT1 inhibitors have shown higher response rates in a basket trial in patients with AKT1 E17K-mutated tumours; however, no SGC patients were included in this trial and they are, therefore, ranked as 3a." (PMID 35267442, 2022). "5-HT can promote the proliferation of tumor cells, which can be attenuated by Akt1 deletion." (PMID 35664068, 2022). "AKT1 acts as an oncogene across many tumor types, including HCC." (PMID 36559697, 2022). "This indicates that decrease in tumor phospho‐Akt1/2/3 levels is not dependent on KRAS mutation status." (PMID 34919787, 2022). "CircNRIP1, a tumor promotor, may influence AKT1 expression in gastric cancer by binding to miR-149-5p." (PMID 34840568, 2021). "Training decreased AKT1 protein expression in the tumour group (T + WBV)." (PMID 34732809, 2021). "Western blot analysis further confirmed that the upregulation of circPSMA1 might increase the expression of Akt1, cyclin D1, and β-catenin but suppress the expression of Bax in xenograft tumor tissues." (PMID 33911067, 2021). "Interestingly, total protein expression of AKT1 was significantly decreased by WBV training in the tumour mice (T + WBV), bringing it down to the level of the control group (C)." (PMID 34732809, 2021). "The results of this integrative cBioPortal analysis suggest that genes AKT3, CHUK and PTEN behave like tumor suppressors, while AKT1, AKT2, EGFR, and PIK3AP1 show oncogenic behavior and are involved in enhanced activity of the EGFR-PI3K-AKT-mTOR signaling pathway." (PMID 34209611, 2021).